BAX (BCL2 associated X, apoptosis regulator)
Diseases named in the same sentence as BAX in open-access papers (continued):
Sharing a sentence is not in itself a finding about the gene and the disease.
epilepsy (4 papers, 2013 to 2025). A brain disorder characterized by episodes of abnormally increased neuronal discharge resulting in transient episodes of sensory or motor neurological dysfunction, or psychic dysfunction. "Neuronal death seen in epilepsy is caused in part by the pro-apoptotic protein Bax, which is encoded by the BAX gene." (PMID 40540445, 2025). "Beside, an aberrant expression pattern of BAX and Bcl-XL has been reported to participate in several other neurological disorders including epilepsy with focal cortical dysplasia and hippocampal sclerosis." (PMID 36515436, 2022). "An increase in cell death or a decrease in apoptosis might result from BAX dysregulation, which can aggravate epilepsy." (PMID 40540445, 2025). "Notably, our study is the first to demonstrate EGCG’s ability to restore the normal balance between BCL2 and BAX in the context of epilepsy, paving the way for further research into its potential as a treatment option for managing this challenging condition." (PMID 41523603, 2025). "In the context of epilepsy progression, our research concentrated on how EGCG affects the balance between the anti‐apoptotic protein BCL2 and the pro‐apoptotic protein BAX." (PMID 41523603, 2025). "Our findings suggest that epilepsy results in a 66% decrease in BCL2 gene expression and a 3.34‐fold increase in BAX gene expression relative to the control group." (PMID 41523603, 2025). "Although BAX-/- mice were useful to study hEGCs in the absence of epilepsy, the constitutive deletion of BAX led to effects other than hEGC formation." (PMID 23840835, 2013).
fibrosarcoma (4 papers, 2019 to 2026). A malignant mesenchymal fibroblastic neoplasm affecting the soft tissue and bone. "The levels of Bcl2, BAX, musculoaponeurotic fibrosarcoma (Maf), Nrf2, Keap1, and PGC1α in the hippocampus were assessed using the western blot method." (PMID 37885999, 2023).
head and neck cancer (4 papers, 2010 to 2025). A primary or metastatic malignant neoplasm affecting the head and neck. "Additionally, it was reported that this saponin increased the levels of pro-apoptotic proteins such as cleaved PARP and BAX in head and neck cancer cell lines." (PMID 38146491, 2023). "As demonstrated in several studies, the intricate interplay and balance between BAX and BCL-2 is critical in regulating apoptosis and plays a pivotal role in the pathophysiology of head and neck cancer." (PMID 39966442, 2025). "BAX activation, conformation change of the Bax protein and its transfer to the outer mitochondrial membrane were also observed in CAPE-treated head and neck cancer cell lines." (PMID 32752091, 2020). "In accordance with other findings, silencing of GRP78 increased BAX and Caspase3 but reduced the expression of p-MAPK in head and neck cancer initiating cells." (PMID 20979610, 2010).
Hepatic steatosis (4 papers, 2014 to 2023). Steatosis is a term used to denote lipid accumulation within hepatocytes.
Insulin resistance (4 papers, 2022 to 2025). Increased resistance towards insulin, that is, diminished effectiveness of insulin in reducing blood glucose levels. "Over-stabilized MDM2 induces cytoplasmic accumulation of NDUFS1, disrupting mitochondrial super-complex assembly, enhancing ROS production, and initiating BIM-mediated BAK/BAX-dependent apoptosis—events that lead to insulin resistance." (PMID 41459066, 2025).
liver fibrosis (4 papers, 2021 to 2024). "The expression levels of apoptosis-related proteins BAX, Caspase9, Caspase8, and Caspase3 were all reduced in the liver tissues of mice with CCl4-induced liver fibrosis." (PMID 39850561, 2024). "Quercetin, known for its strong antioxidant and anti-inflammatory properties, has been found to inhibit HSCs activation by affecting the NF-κB/MAPK and Bcl-2/BAX pathways, thereby delaying the progression of liver fibrosis." (PMID 39185304, 2024). "Hesperidin and naringenin in CRP affect the apoptosis pathway by acting on CASP3, BAX, and BCL2, reducing the likelihood of liver fibrosis." (PMID 33912040, 2021). "In vitro experiments suggested that the mechanism may involve hesperidin and naringenin acting on CASP3, BAX, and BCL2 to affect the apoptosis pathway, attenuating liver fibrosis." (PMID 33912040, 2021).
mantle cell lymphoma (4 papers, 2018 to 2025). Mantle cell lymphoma is a rare form of malignant non-Hodgkin lymphoma affecting B lymphocytes in the lymph nodes in a region called the ``mantle zone''. "Venetoclax resistance mechanisms are not limited to alterations only in BCL2, as acquired mutations in pro-apoptotic BAX have been identified in mantle cell lymphoma, CLL, and AML, but none of our acquired venetoclax-resistant DLBCL lines generated a BAX mutation." (PMID 38893249, 2024). "In mantle cell lymphoma (MCL), research on PRMT5 inhibition showed that activating pro-apoptotic BCL-2 family genes such as BAX enhances cell sensitivity to venetoclax." (PMID 39685591, 2024).
Myocardial fibrosis (4 papers, 2019 to 2025). "Metabolic characteristics, cardiac function and morphology, myocardial remodeling, myocardial fibrosis (collagen III, α-SMA, and TGF-β), oxidative stress (NRF2, HO-1, SOD, and NOX4), and apoptosis (BAX, Bak, Bcl-2, and Bcl-XL) were analyzed 24 weeks after the different treatments." (PMID 34520392, 2021). "SPD treatment also decreased the ratio of BAX to BCL2 expression and percentage of TUNEL-positive nuclei as well as inhibited myocardial fibrosis (collagen deposition) within the myocardium of IUH-exposed neonates, reversing the effects seen under hypoxia exposure." (PMID 31217839, 2019).
myocardial ischemia (4 papers, 2021 to 2025). A disorder of cardiac function caused by insufficient blood flow to the muscle tissue of the heart. "A protective component of GSK-3β inhibition during myocardial ischemia and reperfusion is to increase the threshold for mPTP opening as well as prevent BAX from translocating to the mitochondrial membrane." (PMID 34572418, 2021). "We employed a mouse I/R model and used sh-RNA and USP7 inhibitor P5091 to inhibit USP7 and a Western blot to measure the expression of pro-apoptotic protein BAX and examined whether USP7 can regulate myocardial ischemia/reperfusion damage by altering apoptosis." (PMID 35710902, 2022).
non-Hodgkin lymphoma (4 papers, 2003 to 2022). Distinct from Hodgkin lymphoma both morphologically and biologically, non-Hodgkin lymphoma (NHL) is characterized by the absence of Reed-Sternberg cells, can occur at any age, and usually presents as a localized or generalized lymphadenopathy associated with fever and weight loss. "In diffuse aggressive non-Hodgkin's lymphoma, reduced BAX expression was associated with a lower 8-year survival." (PMID 12592374, 2003). "In an association study between polymorphisms of - 938C/A and Thr43Ala in the BCL-2 gene and G - 248A in the BAX gene and the risk of developing non-Hodgkin lymphoma (NHL), it was reported that the - 248AG + AA genotype of the BAX gene might be susceptible genotypes for NHL." (PMID 26744613, 2016).
oral squamous cell carcinoma (4 papers, 2013 to 2021). "The depletion of CELF1 reduces proliferation and increases apoptosis in oral squamous cell carcinoma where CELF1 associates directly with the 3′UTR of BAD (BCL2 Associated Agonist Of Cell Death), BAX (BCL2 Associated X, Apoptosis Regulator) and JunD mRNAs and mediates their rapid decay." (PMID 34681716, 2021). "PAX9 is one of the nine members of "paired box” (PAX)-containing transcription factor family and its inhibition has been shown to induce apoptosis with increased cleavage of caspase-3 and PARP, increased expression of BAX and decreased expression of BCL-2 in oral squamous cell carcinoma." (PMID 28572861, 2017).
asthma (3 papers, 2021 to 2022). "Importantly, BAK/BAX-deficient MSCs were unable to inhibit asthma and EAE to the full extent as nontargeted MSCs, indicating that a key cell-intrinsic property of MSCs as a therapeutic agent is their apoptosis." (PMID 34764248, 2021).
brain injuries (3 papers, 2017 to 2022). "BAX is a pro-apoptotic protein and its activation is responsible for developmental cell death also during brain injuries." (PMID 28769794, 2017). "Disrupting the VDAC2:BAX interaction could be exploited to limit pathological apoptosis following traumatic or ischemic brain injuries since differentiated neurons lack functional BAK40." (PMID 30478310, 2018).
breast invasive cancer (3 papers, 2021 to 2024). "The analysis of the clinical stages of patients with breast invasive carcinoma indicated that the BAX, BCL2L1, CASP8, CASP9, RELA, and NFKBIA gene expression levels were higher in stages 3 and 4 for all BRCA patients, and in stage 4 for BRCA-LumA patients, than in other clinical stages." (PMID 38542508, 2024).
cognitive deficits (3 papers, 2013 to 2025). "In summary, this study demonstrates that CP induces cognitive deficits associated with increased hippocampal levels of inflammatory markers (IL-1β, IL-6, NF-κB, and TNF-α) and apoptotic markers (caspase-3 and BAX)." (PMID 41256255, 2025). "Indeed, it is known that both BAX-/- mice and SE produce cognitive deficits." (PMID 23840835, 2013).
cutaneous melanoma (3 papers, 2021 to 2024). A primary melanoma arising from atypical melanocytes in the skin. "A germline deletion in the BAX gene was identified in a patient with both cutaneous melanoma and a gastrointestinal stromal tumor, and somatic BAX protein alterations were observed in various cancers." (PMID 38892746, 2024).
cyst (3 papers, 2017 to 2021). A sac-like closed membranous structure that may be empty or contain fluid or amorphous material. "However, a dose of 45 Gy significantly suppressed the expression of BCL-2 and BAX in the lung tissues involved by the cyst, suggesting beneficial effects on the host." (PMID 35274045, 2021). "BAX expression was significantly downregulated in the cyst after exposure to a dose of 45 and 60 Gy, rather than that of 30 Gy, indicating 45 and 60 Gy of irradiation reversed the cell death induced by the cyst." (PMID 35274045, 2021). "This was supported by an induction of caspase-3 and gadd45a expression in the cyst and a downregulation of BCL-2 and BAX in the adjacent lung tissues." (PMID 35274045, 2021). "On this basis, we speculated that 45 Gy might be a safe and effective dose for treating pulmonary hydatidosis in sheep, which induced lower expression of caspase-3 and gadd45a in the cyst and a downregulation of BCL-2 and BAX in the adjacent lung tissues." (PMID 35274045, 2021).
diabetic nephropathy (3 papers, 2020 to 2023). "Previous research reported SA possessed anti-apoptotic activity against diabetic nephropathy via suppression of BAX expression and increase of BCL-2 expression." (PMID 35432808, 2021). "BAX, a well-known marker of apoptosis, was evaluated by immunohistochemistry to assess the impact of REO on apoptosis in the diabetic nephropathy rat model." (PMID 37016650, 2023).
endometrial adenocarcinoma (3 papers, 2013 to 2022). "A recent study showed that the activated estrogen receptor can suppress the expression of BAX by up-regulating a group of miRNAs including hsa-let-7 family members in endometrial adenocarcinoma and precancerous lesions." (PMID 23705682, 2013). "In contrast, mifepristone could inhibit cell growth and induce apoptosis in Ishikawa endometrial adenocarcinoma cells through caspase-3 activation and regulating apoptotic genes such as BCL2/BAX and FAS/FASLG." (PMID 35869506, 2022). "In addition, endometrial adenocarcinoma patients expressed significantly higher levels of MCL-1 and lower levels of BAK and BAX, whereas BCL-xL and p21 levels did not significantly differ between the two groups." (PMID 29358688, 2018).
gastric adenocarcinoma (3 papers, 2016 to 2025). "It has been reported that in human gastric adenocarcinoma BAX expression is significantly down-regulated during the first 24 h of treatment with etoposide, cisplatin or taxol, however levels gradually increased in the next 48 and 72 h." (PMID 26861394, 2016). "Another work showed that the antineoplastic drug 5-FU decreased the mRNA levels of Bcl-2 in the first 48 h, which coincided with the up-regulation of BAX, after 72 h of treatment Bcl-2 was up-regulated and the levels of BAX were decreased in human gastric adenocarcinoma." (PMID 26861394, 2016).
Hodgkins lymphoma (3 papers, 2017 to 2024). A heterogeneous group of malignant lymphoid neoplasms of B-cell origin characterized histologically by the presence of Hodgkin and Reed-Sternberg (HRS) cells in the vast majority of cases. "For example, palmitoylation of the pro‐apoptotic protein BAX has been found to be reduced in Hodgkin lymphoma B cell lines in comparison to control B cells and correlated with reduced BAX activity." (PMID 38013654, 2024).
Hypertension (3 papers, 2022 to 2024). The presence of chronic increased pressure in the systemic arterial system. "We evaluated the intrinsic pathway of apoptosis and noticed that arterial hypertension generated an increase in the antiapoptotic protein BCL-2 and a decrease in the proapoptotic protein BAX and consequently considerably decreased the BAX/BCL-2 ratio." (PMID 36865350, 2023). "Our group demonstrated that moderate or intense resistance or aerobic exercise promotes alteration in urogenital apoptosis, increasing BAX and reducing BCL-2, even if the animals are submitted to high-fat diets or have arterial hypertension." (PMID 36865350, 2023). "The BAX/BCL-2 ratio was decreased in the SHRc group, perceived as a reflection of the imbalance generated by arterial hypertension; thus, the SHR+T group presented increases in this ratio through regulation of the imbalance generated by hypertension (p = 0.033)." (PMID 36865350, 2023). "rs113360897, rs611251, rs11668424, rs1805419 of BAX, and rs2936839 of PEBP1 exhibited pleiotropy, wherein rs113360897, rs611251, and rs2936839 were related to red cell distribution width and inflammation in patients with non-dipper hypertension." (PMID 39769348, 2024).
ischemic stroke (3 papers, 2017 to 2022). A stroke disorder caused by obstruction of blood flow to the brain, due to thrombotic (local blood clot formation) or embolic (due to a blood clot or other material traveling from another site) event. "Hence, the concurrent enhancement of Bcl-2 and suppression of proapoptotic factors such as caspase-3 and BAX may be contributing to the decrease of neuronal cell death following ischemic stroke." (PMID 33664650, 2021). "In this study, artemisinin reversed the ischemic stroke-induced decrease in the phosphorylation of ERK and CREB and increase in the ratio of BAX/BCL2." (PMID 35864966, 2022).
memory impairment (3 papers, 2020 to 2025). "Strawberry and selenium, when administered individually, significantly attenuated memory impairment, oxidative stress, neuroinflammation, and apoptosis, as evidenced by marked normalization of Nrf2/HO-1, TAC, SOD, MDA, TLR4/NF-κB/TNF-α, NLRP3/CASP-1/IL-1β, and BAX/Bcl-2 signaling." (PMID 41471381, 2025).
myelogenous leukemia (3 papers, 2022 to 2024). "BAX mutations have also been detected in the myeloid compartment of CLL patients with clonal hematopoiesis who were treated with VEN, which further supports the notion that BAX has a critical role in BH3 mimetic–induced death of myeloid leukemia cells." (PMID 37088806, 2023).
osteoarthritis (3 papers, 2011 to 2024). A noninflammatory degenerative joint disease occurring chiefly in older persons, characterized by degeneration of the articular cartilage, hypertrophy of bone at the margins and changes in the synovial membrane. "TNFRSF11B and BAX have been reported to be associated with osteoarthrosis by previous studies." (PMID 21829570, 2011). "Moreover, increased levels of 4-HNE and/or BAX have been detected in the AMG and PAG of nerve-injured animals, and in the AMG of animals with osteoarthritis pain." (PMID 35883812, 2022).
prostate tumor (3 papers, 2019 to 2023). "Similar to observations of AR and IGF-1 expression, levels of the anti-apoptotic protein BCL-2 and the ratio of BCL-2/BAX, a marker of prostate tumor proliferative potential, were higher in animals submitted to the CS protocol than in all other groups." (PMID 32321149, 2020).
psoriasis (3 papers, 2018 to 2025). An autoimmune condition characterized by red, well-delineated plaques with silvery scales that are usually on the extensor surfaces and scalp. "The distinction was that, in terms of both gene expression and ROC curve, the only element in the psoriasis validation set that matched the trend of the AD dataset was BAX." (PMID 38774875, 2024). "Additionally, studies have shown that other genes such as FAS, BAX, and BCL-2 also exhibit different expression patterns in the skin of psoriasis patients, and these genes are directly involved in the regulation of apoptosis." (PMID 40557155, 2025).
renal carcinoma (3 papers, 2019 to 2024). A carcinoma arising from the epithelium of the renal parenchyma or the renal pelvis. "Our results showed that nobiletin treatment decreased BCL2 expression in renal carcinoma cells, whereas that of BAX was increased." (PMID 31354472, 2019).
retinoblastoma (3 papers, 2014 to 2025). A malignant tumor that originates in the nuclear layer of the retina. "In this study, we found that inhibition of PAX6 in human retinoblastoma cell lines led to a low apoptotic rate which was supported by the changes in the levels of apoptosis-related proteins (Bcl-2 and BAX)." (PMID 24939714, 2014). "Interestingly, treatment of Y-79 cells, human retinoblastoma cells that endogenously express α3β2, with recombinant RS1 resulted in decreased expression of the pro-apoptotic BCL-2 associated X protein (BAX)." (PMID 40558505, 2025). "However, the level of BAX was downregulated in both retinoblastoma cell lines (t=4.51, P<0.05; and t=67.96, P<0.01, resp." (PMID 24939714, 2014).